KIF2C (kinesin family member 2C)
Description:
In complex with KIF18B, constitutes the major microtubule plus-end depolymerizing activity in mitotic cells. Regulates the turnover of microtubules at the kinetochore and functions in chromosome segregation during mitosis. Plays a role in chromosome congression and is required for the lateral to end-on conversion of the chromosome-microtubule attachment.
Synonyms: MCAK; KNSL6; CT139
Tractability: Small molecule: a structure with a bound ligand is known; a high-quality ligand is known. PROTAC: UniProt records ubiquitination sites on it; ubiquitination databases record sites on it.
Target class: Other cytosolic protein
Gene: Protein-coding gene on chromosome 1 (44,739,817 to 44,767,767, forward strand). Ensembl gene ENSG00000142945.
Subcellular location: Cytoplasm, cytoskeleton; Nucleus; Chromosome, centromere; Chromosome, centromere, kinetochore
Subcellular location (Human Protein Atlas): Centrosome; Midbody; Nucleoplasm; Cytosol
Pathways (Reactome):
Cell Cycle: Amplification of signal from unattached kinetochores via a MAD2 inhibitory signal; EML4 and NUDC in mitotic spindle formation; Mitotic Prometaphase; Resolution of Sister Chromatid Cohesion; Separation of Sister Chromatids
Hemostasis: Kinesins
Immune System: MHC class II antigen presentation
Signal Transduction: RHO GTPases Activate Formins
Vesicle-mediated transport: COPI-dependent Golgi-to-ER retrograde traffic
Gene Ontology:
Molecular function: microtubule plus-end binding; protein binding; centromeric DNA binding; microtubule motor activity; ATP binding; microtubule binding
Biological process: attachment of mitotic spindle microtubules to kinetochore; establishment or maintenance of microtubule cytoskeleton polarity; metaphase chromosome alignment; microtubule depolymerization; mitotic metaphase chromosome alignment; regulation of chromosome segregation; microtubule-based movement; mitotic sister chromatid segregation
Cellular component: chromosome, centromeric region; kinetochore; membrane; microtubule cytoskeleton; microtubule plus-end; centrosome; cytoplasmic microtubule; cytosol; kinesin complex; spindle; cytoskeleton; nucleus
Genetic constraint (gnomAD): Loss-of-function variants: 26 observed, 83.6 expected, observed/expected ratio (o/e) 0.31, 90% interval 0.23 to 0.43. The upper end of that interval is the gene's LOEUF score, 0.43, which puts it in group 1 of 6, group 1 being the genes least tolerant of losing a copy. Missense variants: 700 observed, 868.33 expected, observed/expected ratio (o/e) 0.81, 90% interval 0.76 to 0.86. Synonymous variants: 291 observed, 312.08 expected, observed/expected ratio (o/e) 0.93, 90% interval 0.85 to 1.03.
Homologues: Orthologues: chimpanzee KIF2C (99% identical), macaque KIF2C (98% identical), dog KIF2C (92% identical), rabbit KIF2C (91% identical), pig KIF2C (91% identical), mouse Kif2c (87% identical), guinea pig KIF2C (87% identical), rat Kif2c (87% identical), tropical clawed frog kif2c (65% identical), Drosophila melanogaster Klp10A (48% identical), Drosophila melanogaster Klp59D (43% identical), Caenorhabditis elegans klp-7 (42% identical), and 1 more. Paralogues in human: KIF2A (54% identical), KIF2B (42% identical), KIF24 (33% identical), KIF14 (22% identical), KIF1A (21% identical), KIF1B (21% identical), KIF16B (20% identical), KIF13A (20% identical), KIF13B (20% identical), KIF7 (20% identical), KIF1C (20% identical), KIF21A (20% identical), and 29 more.
Diseases named in the same sentence as KIF2C in open-access papers:
KIF2C is named in the same sentence as 90 diseases in open-access papers, as found by Europe PMC text mining. Sharing a sentence is not in itself a finding about the gene and the disease. The quoted sentences say what the papers report.
breast cancer (56 papers, 2008 to 2026). A primary or metastatic malignant neoplasm involving the breast. "Knockdown of either PRC1 or KIF2C inhibited proliferation of multiple breast cancer cell lines, which was associated with morphological changes especially during mitosis, in these cancer cells." (PMID 38344808, 2024). "Several previous studies have shown that KIF2C and other kinesins were overexpressed in breast cancer and associated with worse prognosis." (PMID 37016301, 2023). "In summary, the bioinformatic analysis showed that KIF2C was upregulated in breast cancer and other types of cancer, and the high KIF2C expression was associated with poor prognosis in breast cancer." (PMID 37016301, 2023). "Aberrant expression of KIF2C are frequently implicated in an oncogenic state and promotion of tumorigenesis in several cancer tissues, including breast cancer and hepatocellular carcinoma." (PMID 37968758, 2023). "In breast cancer, MCAK/KIF2C is part of the PAM50 signature for classification of breast cancer subtypes where high expression is associated with the basal subtype." (PMID 37444419, 2023). "The results of tumor mutational burden analysis also showed that breast cancer patients in the high KIF2C expression group had a higher tumor mutational burden compared with the low expression group." (PMID 37016301, 2023). "In addition, we found that high expression of the KIF2C gene was associated with a higher tumor mutational burden and a favorable response to immunotherapy in breast cancer." (PMID 37016301, 2023). "Our data suggest that KIF2C may be involved in the development of higher grade of breast cancer, and a high level of KIF2C is significantly associated with poor OS in breast cancer patients." (PMID 37016301, 2023). "Together, these discoveries revealed that high expression of KIF2C may be associated with the higher immune cell infiltration, higher tumor mutational burden, and better response to immunotherapy in breast cancer." (PMID 37016301, 2023). "We found that higher KIF2C expression was associated with poor OS in breast cancer." (PMID 37016301, 2023). "Finally, our results revealed that KIF2C was significantly related to immune cell infiltration, tumor mutational burden, and immunotherapy in patients with breast cancer." (PMID 37016301, 2023). "We further demonstrated that the expression of KIF2C was positively associated with immune cell infiltration of the tumor microenvironment, suggesting that KIF2C may act as a potential prognostic biomarker for breast cancer immunotherapy." (PMID 37016301, 2023). "Although some studies have demonstrated that KIF2C can affect the prognosis of breast cancer patients, we believe that this difference is more due to the stratification of the population and the choice of statistical methods." (PMID 41333555, 2025). "A recent analysis of breast cancer samples integrated in The Cancer Genome Atlas (TCGA) revealed that KIF2C, along with two cell cycle master regulators CCNB1 (cyclin B1) and Plk1, is a promising target for breast cancer therapy." (PMID 38344808, 2024). "In summary, these reports corroborate KIF2C as a prognostic biomarker and novel compounds enable KIF2C to be a potential target for breast cancer therapy." (PMID 38344808, 2024). "In conclusion, KIF2C increases breast cancer tumorgenicity, malignancy and is sufficient to induce chemoresistance by multiple mechanisms." (PMID 38344808, 2024). "Breast cancer represents the best studied cancer entity correlated with KIF2C’s expression, prognostic value and involvement in therapy resistance." (PMID 38344808, 2024). "In this study, we provided several lines of evidence to demonstrate a significant positive correlation between KIF2C expression and the infiltrating immune cells in breast cancer." (PMID 37016301, 2023). "We identified age, stage, estrogen receptor (ER) and KIF2C expression as OS-related independent prognosis factors for breast cancer." (PMID 37016301, 2023).
breast cancer (continued). "In line with our studies, other groups reported that ASPM, KIF20A, TPX2, AURKA and KIF2C are among the top 11 up-regulated hub key genes identified as potential breast cancer prognostic biomarkers." (PMID 37835564, 2023). "We further examined KIF2C expression in breast cancer and matched normal tissues using downloaded data from the TCGA database and the GSE36295 dataset." (PMID 37016301, 2023). "To explore the potential regulatory mechanisms of KIF2C expression in breast cancer, we constructed a KIF2C-related ceRNA network." (PMID 37016301, 2023). "In this study, we conducted a serial of bioinformatics analysis to investigate the role of KIF2C in the occurrence and progression of breast cancer." (PMID 37016301, 2023). "Up-regulation of KIF2C has been observed in various cancers, including breast cancer, hepatocellular carcinoma, colorectal cancer, gastric cancer, gliomas, endometrial cancer, and non-small cell lung cancer." (PMID 37016301, 2023). "The results showed that, in agreement with our bioinformatic analysis, KIF2C was upregulated in breast cancer tissues, as compared to the adjacent normal tissues." (PMID 37016301, 2023). "Further in vitro and in vivo studies are needed to elucidate the role of KIF2C in breast cancer immune cell infiltration in the future." (PMID 37016301, 2023). "KIF2C has been demonstrated to play a crucial role in various diseases, such as hepatocellular carcinoma, endometrial carcinoma, breast cancer, and bladder cancer." (PMID 37711155, 2023). "KIF2C was overexpressed in breast cancer and was positively correlated with immune cell infiltration and immunotherapy response." (PMID 37016301, 2023). "In the present study, KIF2C was found to be up-regulated in breast cancer in all subtypes of breast cancer compared to normal tissues." (PMID 37016301, 2023). "The TBX15/miR-152/KIF2C pathway regulates adriamycin resistance in breast cancer by promoting PKM2 ubiquitination." (PMID 35456460, 2022). "Previous research has revealed that KIF2C is substantially expressed in liver cancer, breast cancer, endometrial carcinoma, lung cancer, glioma, bladder cancer, colorectal cancer, esophageal squamous cell carcinoma, cervical cancer, and thyroid cancer." (PMID 35720323, 2022). "It was reported that KIF2C expression was significantly upregulated in HCC and breast cancer, and that KIF2C up-regulation was associated with a poor prognosis." (PMID 35360870, 2022). "Up-regulation of KIF2C has been documented in multiple human cancers, such as breast cancer, gastric cancer, colorectal cancer, glioma, liver cancer and non-small cell lung cancer." (PMID 34820170, 2021). "The further study would be warranted to identify potential translation significance of TBX15 / miR-152 / KIF2C / PKM2 in clinical diagnosis or new treatment option for overcoming DOX resistance in breast cancer." (PMID 34663310, 2021). "In breast cancer, comprehensive bioinformatics analyses revealed that tumor-related KIF2C correlated with poor outcomes of breast cancer patients and acts as a potential prognostic biomarker." (PMID 34650608, 2021). "TBX15 and miR-152 overexpression suppressed autophagy and glycolysis in breast cancer cells, while KIF2C overexpression reversed the process." (PMID 34663310, 2021). "Poorly differentiated breast cancer tumors are characterized by specific set of over-expressed genes (e.g., UBE2C, CCNB2, CDK1, KIF2C, NDC80, and CCNB2) and are associated with more aggressive tumors and lower survival." (PMID 34300003, 2021). "Our studies demonstrate that TBX15/miR-152 pathway is downregulated in DOX-resistant breast cancer tissues and that KIF2C expression is induced by miR-152 suppression." (PMID 34663310, 2021). "We found that KIF2C expression levels were significantly higher in breast cancer tissues than those in the adjacent groups." (PMID 34663310, 2021).
breast cancer (continued). "We found that KIF2C levels were highly expressed in DOX-resistant breast cancer tissues and cells, and KIF2C was a potential target of miR-152." (PMID 34663310, 2021). "TBX15/miR-152 blocked autophagy and glycolysis in DOX-resistant breast cancer cells by targeting KIF2C." (PMID 34663310, 2021). "Elevated expression levels of kinesins KIF14, KIF4A, KIF20A, and KIF23, KIF2C, and KIFC1 have been reported in breast cancer cell lines, other kinesins KIF10, KIF18A, and KIF15 have been linked to prognostic indicators in breast cancer patients." (PMID 32346924, 2020). "Five hub genes, including TPX2, KIF2C, CDCA8, BUB1B, and CCNA2, were validated to be notably associated with the shorter DMFS of breast cancer in the patient cohort based on KM Plotter." (PMID 31285741, 2019). "Accordingly, KIF2C has been reported to be a promising therapeutic target in invasive ductal carcinoma of breast cancer based on PPI network analysis." (PMID 31285741, 2019). "Overall, we identified five genes (TPX2, KIF2C, CDCA8, BUB1B, and CCNA2) associated with distant metastasis, indicating these genes as potential biomarkers for assessing the risk of breast cancer recurrence and distant metastasis." (PMID 31285741, 2019). "According to the PPI networks, five hub genes (TPX2, KIF2C, CDCA8, BUB1B, and CCNA2) were identified as key genes associated with breast cancer progression." (PMID 31285741, 2019). "While the underlying mechanisms are not clear, further investigations are needed to identify the role of KIF2C in breast cancer." (PMID 29467930, 2018). "Further, specific small interfering RNAs effectively suppressed KIF-2C expression and inhibited the growth of breast cancer and prostate cell lines that express high levels of KIF-2C." (PMID 27563815, 2016). "Although trace levels of KIF-2C are expressed in healthy organs, its levels are high in testis as well as in colorectal cancer, gastric cancer, breast cancer, prostate cancer, and glioma." (PMID 27563815, 2016). "Among kinesin family members, the function of KIF2C/MCAK in gastric, colorectal and breast cancers has been studied." (PMID 24950762, 2014). "Protein regulator of cytokinesis 1 (PRC1) is essential for organization of central spindle and midzone formation, whose interaction with KIF2C has been shown to be involved in breast cancer tumorigenesis." (PMID 21501490, 2011). "KIF2C is overexpressed in breast cancer cells and functional analysis suggest a link between overexpression and carcinogenesis." (PMID 20042109, 2009). "Additionally, the silencing of KIF2C was also associated with decreased p-MEK and p-ERK signals, reducing proliferation, migration and invasion capacity of the epithelial breast cancer cell line HCC1954." (PMID 38344808, 2024). "Moreover, two in vitro studies showed that protein regulator of cytokinesis 1 (PRC1) and KIF2C formed a functional complex and that both were upregulated in several breast cancer cell lines." (PMID 38344808, 2024). "KIF2C’s role in multiple vital functions and its high protein/gene expression will be discussed in various cancer entities including breast cancer, non-small lung cancer, hepatocellular carcinoma and gastric cancer, highlighting its crucial role in carcinogenesis." (PMID 38344808, 2024). "In basal-like breast cancer, KIF2C is a crucial hub gene, together with nine other genes." (PMID 38344808, 2024). "The gene level of KIF2C was found to be correlated with poor outcomes in breast cancer patients." (PMID 38344808, 2024). "We further performed a univariate Cox analysis to determine whether KIF2C was an independent OS factor in breast cancer." (PMID 37016301, 2023).
breast cancer (continued). "Additionally, the TIDE algorithm was used to predict the efficacy of immunotherapy for breast cancer patients in the high and low KIF2C expression groups." (PMID 37016301, 2023). "Collectively, these data suggested that KIF2C expression may be influenced by age and involved in the progression of breast cancer." (PMID 37016301, 2023). "In this study, we assessed the potential of targeting MCAK in cell-line models of triple-negative breast cancer (TNBC) because MCAK/Kif2C is highly expressed in breast cancer, and because anti-MT agents are often first-line therapies for TNBC, which frequently become resistant to these drugs." (PMID 37444419, 2023). "Therefore, KIF2C can serve as a potential biomarker for prognosis and immunotherapy in breast cancer." (PMID 37016301, 2023). "Our results showed that age (HR = 1.04341252, P = 3.17E-08), TNM stage (HR = 2.39546349, P = 8.93E-13), ER (HR = 0.58848779, P = 0.01866529), and high KIF2C expression (HR = 1.60169321, P = 0.02724886) were independent prognostic factors for OS in breast cancer patients." (PMID 37016301, 2023). "We found that KIF2C is positively correlated with immune cell infiltration and immunotherapy response, suggesting that KIF2C might serve as a potential biomarker for prognosis and immunotherapy in breast cancer." (PMID 37016301, 2023). "Up-regulation of KIF2C can promote the disassembly of primary cilia through its MT depolymerizing activity, which may contribute to the pathogenesis of breast cancer." (PMID 37016301, 2023). "The results showed that KIF2C was upregulated in all subtypes of breast cancer." (PMID 37016301, 2023). "KIF2C was remarkably up-regulated in 18 different types of cancers, including breast cancer." (PMID 37016301, 2023). "Our results revealed that KIF2C could act as a potential biomarker for prognosis and immunotherapy of breast cancer." (PMID 37016301, 2023). "KIF2C expression in breast cancer patients with different molecular subtypes was also examined." (PMID 37016301, 2023). "In mammary carcinogenesis, overexpression of KIF2C might be involved in breast carcinogenesis and is a promising therapeutic target as well as a prognostic biomarker for breast cancer." (PMID 34650608, 2021). "Higher expression of KIF2C indicated poor prognosis in breast cancer patients." (PMID 34663310, 2021). "To identify whether KIF2C promotes DOX resistance in breast cancer tissues, we obtained TCGA mRNAs expression data from Breast Cancer, and divided the samples into cancer tissues and adjacent tissue groups." (PMID 34663310, 2021). "In this study, we identified that miR-152 may directly target and decrease KIF2C expression for inhibiting DOX resistance in breast cancer." (PMID 34663310, 2021). "Our data identify a new mechanism by which TBX15 abolishes DOX chemoresistance in breast cancer, and suggest that TBX15/miR-152/KIF2C axis is a novel signaling pathway for mediating DOX resistance in breast cancer through regulating PKM2 ubiquitination and decreasing PKM2 stability." (PMID 34663310, 2021). "However, the role and mechanism by which KIF2C promotes chemoresistance is unclear in breast cancer." (PMID 34663310, 2021). "RNAi based inhibition of KIF2C expression inhibits growth in breast cancer cell lines." (PMID 20042109, 2009). "Notably, KIF2C has been shown to enhance the malignancy of various tumors, including breast cancer, non‐small cell lung cancer (NSCLC), and hepatocellular carcinoma (HCC), with elevated KIF2C expression correlating with poor overall survival and disease‐free survival." (PMID 40292920, 2025). "Moreover, the gene methylation of KIF2C was significantly elevated in luminal A breast cancer samples with prognostic value, together with three other cell cycle and proliferation regulators Ki-67, UBE2C (ubiquitin conjugating enzyme E2C) and HDAC4 (histone deacetylase 4)." (PMID 38344808, 2024).